STAT5B (signal transducer and activator of transcription 5B)
Description:
Signal transducer and transcription activator that mediates cellular responses to cytokines, hormones and growth factors. Binds to the GAS element and activates PRL-induced transcription. Positively regulates hematopoietic/erythroid differentiation. Involved in the oncostatin-M-mediated signaling pathway through type II OSM receptor complex (heterodimers composed of OSMR and IL6ST).
Synonyms: GHISID2; STAT5
Tractability: Small molecule: a high-quality ligand is known; it belongs to a druggable protein family. PROTAC: ubiquitination databases record sites on it; its protein half-life has been measured; a small molecule that binds it is known.
Target class: Transcription factor
Chemical probes: AC-4-130, PD085091
Gene: Protein-coding gene on chromosome 17 (42,199,176 to 42,288,633, reverse strand). Ensembl gene ENSG00000173757.
Subcellular location: Cytoplasm; Nucleus
Subcellular location (Human Protein Atlas): Cytosol
Pathways (Reactome):
Immune System: Growth hormone receptor signaling; Inactivation of CSF3 (G-CSF) signaling; Interleukin-15 signaling; Interleukin-2 signaling; Interleukin-20 family signaling; Interleukin-21 signaling; Interleukin-3, Interleukin-5 and GM-CSF signaling; Interleukin-7 signaling; Interleukin-9 signaling; Prolactin receptor signaling; STAT5 Activation; Signaling by CSF3 (G-CSF)
Disease: STAT5 activation downstream of FLT3 ITD mutants; Signaling by FLT3 fusion proteins; Signaling by cytosolic FGFR1 fusion mutants; Signaling by phosphorylated juxtamembrane, extracellular and kinase domain KIT mutants
Signal Transduction: Downstream signal transduction; Erythropoietin activates STAT5; Signaling by Leptin; Signaling by SCF-KIT
Developmental Biology: Differentiation of naive CD4+ T cells to T helper 2 cells (Th2 cells)
Gene Ontology:
Molecular function: DNA-binding transcription activator activity, RNA polymerase II-specific; identical protein binding; nuclear glucocorticoid receptor binding; protein binding; protein homodimerization activity; chromatin binding; DNA-binding transcription factor activity; DNA-binding transcription factor activity, RNA polymerase II-specific; protein dimerization activity; RNA polymerase II cis-regulatory region sequence-specific DNA binding; DNA binding
Biological process: cellular response to hormone stimulus; erythropoietin-mediated signaling pathway; growth hormone receptor signaling pathway via JAK-STAT; positive regulation of erythrocyte differentiation; response to estradiol; cell surface receptor signaling pathway via JAK-STAT; cellular response to epidermal growth factor stimulus; cellular response to growth factor stimulus; cytokine-mediated signaling pathway; defense response; positive regulation of transcription by RNA polymerase II; regulation of cell population proliferation; regulation of multicellular organism growth; regulation of transcription by RNA polymerase II; response to peptide hormone; taurine metabolic process; regulation of DNA-templated transcription; regulation of hemopoiesis; signal transduction
Cellular component: cytoplasm; nucleus; chromatin; cytosol; nucleoplasm; RNA polymerase II transcription regulator complex
Genetic constraint (gnomAD): Loss-of-function variants: 21 observed, 109.22 expected, observed/expected ratio (o/e) 0.19, 90% interval 0.14 to 0.28. The synonymous counts are far from expectation, so gnomAD's model fits this gene poorly and the ratio says little. Missense variants: 558 observed, 1,003.4 expected, observed/expected ratio (o/e) 0.56, 90% interval 0.52 to 0.6. Synonymous variants: 321 observed, 398.7 expected, observed/expected ratio (o/e) 0.81, 90% interval 0.73 to 0.88.
Gene-disease validity (ClinGen):
ClinGen rates the evidence that STAT5B causes each of these diseases.
growth hormone insensitivity with immune dysregulation 1, autosomal recessive (autosomal recessive): Definitive.
growth hormone insensitivity syndrome with immune dysregulation 2, autosomal dominant (autosomal dominant): Moderate.
Cancer hallmarks: escaping programmed cell death (promotes); escaping immune response to cancer; proliferative signalling (promotes); invasion and metastasis (promotes); tumour promoting inflammation; angiogenesis (promotes)
Homologues: Orthologues: macaque STAT5B (99% identical), pig STAT5B (97% identical), mouse Stat5b (97% identical), dog STAT5B (96% identical), rabbit STAT5B (96% identical), guinea pig STAT5B (94% identical), chimpanzee STAT5B (93% identical), rat Stat5b (92% identical), tropical clawed frog stat5b (87% identical), zebrafish stat5a (80% identical), zebrafish stat5b (74% identical), Drosophila melanogaster Stat92E (32% identical). Paralogues in human: STAT5A (93% identical), STAT6 (37% identical), STAT3 (28% identical), STAT4 (28% identical), STAT1 (27% identical), STAT2 (26% identical).
Diseases named in the same sentence as STAT5B in open-access papers:
STAT5B is named in the same sentence as 220 diseases in open-access papers, as found by Europe PMC text mining. Sharing a sentence is not in itself a finding about the gene and the disease. The quoted sentences say what the papers report.
leukemia (40 papers, 2012 to 2025). A malignant (clonal) hematologic disorder, involving hematopoietic stem cells and characterized by the presence of primitive or atypical myeloid or lymphoid cells in the bone marrow and the blood. "Replacement with a histidine causes a structural change in STAT5B, rendering it resistant to dephosphorylation, which promotes continuous activation and contributes to the aggressive nature of the leukemia." (PMID 40140631, 2025). "Data on the frequencies of STAT3 and STAT5B gene mutations in γδT-LGL leukemia are rare and inconsistent." (PMID 39161592, 2024). "Here, we report clinical findings, immunophenotypic data, TCR-γ, -β, and -δ gene rearrangements, and STAT3 and STAT5B mutation frequencies for a series of 15 patients with γδT-LGL leukemia associated with rheumatologic diseases." (PMID 39161592, 2024). "For example, the second most frequent mutation in STAT5B (Y665F) represents a drastic change in polarity, and leads to aggressive leukemias." (PMID 37207333, 2023). "STAT5B has been defined as more important than STAT5A in BCR/ABL-induced leukemia, explaining the high frequency of STAT5B mutations in hematopoietic malignancies." (PMID 34055801, 2021). "A downregulated IFN response was also observed in patients suffering from leukemia carrying STAT5B mutations." (PMID 30679796, 2019). "The majority of STAT mutations occur in the SH2 and C-terminal domains of STAT3 and STAT5B and associate with leukemias and lymphomas." (PMID 31684144, 2019). "In line, transcriptional analysis of STAT5B-mutated leukemia patient samples revealed a downregulated IFN response." (PMID 30679796, 2019). "The most frequent STAT5B mutation, Asp642His (N642H), has been found in over 90 leukemia and lymphoma patients." (PMID 29200404, 2018). "Supporting the correlation between mutational pattern and leukemic LGL phenotype, STAT5b mutations were specifically found only in CD4+ T-LGL leukemia." (PMID 28977911, 2017). "Vbeta 13.1 prevalence observed in CD4+ T-LGL leukemia was similarly found in STAT5b mutated patients (2/5, 40%)." (PMID 28977911, 2017). "Constitutive STAT5 activation is also observed in the majority of leukemias and many solid tumors, encoding by Stat5a and Stat5b genes on human chromosome 17 in a locus that also contains the Stat3 gene." (PMID 28422733, 2017). "Nevertheless, when crossed to additional leukemia predisposing backgrounds (e.g. Ebf1 or Ikzf1, Stat5b or BCR-ABLp190) or challenged through external stressors (e.g. infection exposure or antibiotics) Pax5± mice develop an aggressive BCP-ALL that closely resembles the human disease." (PMID 40394211, 2025). "MV4-11 cells present a FLT3-ITD mutation that renders a hyper-active and hyper-phosphorylated form of the FLT3 tyrosine kinase, which in turns phosphorylates STAT5B at Try699 to drive leukaemia progression." (PMID 40082888, 2025). "Its cell-permeable prodrug 17 (dubbed Pomstafib-2-CR) inhibits phosphorylation of STAT5b in cultured human leukemia cells with slightly higher activity and selectivity over STAT5a than Pomstafib-2, the prodrug corresponding to Stafib-2." (PMID 41320753, 2025). "The findings expand understanding of STAT5B beyond its established role in leukemias, highlighting a broader tumor-suppressive function." (PMID 41301421, 2025). "Recently, gain-of-function mutations in STAT5B and STAT3 have been found in patients with various types of leukemia and lymphomas." (PMID 36765714, 2023). "STAT proteins, especially STAT3 and STAT5B have been identified as potential pharmaceutical targets in a range of oncological conditions, including various types of leukemias and solid cancers." (PMID 37207333, 2023). "For instance, Stat5b-CA x Ebf1+/− and Stat5b x Pax5+/− transgenic mice develop rapid onset leukemia with complete penetrance whereas leukemogenesis is somewhat less efficient when crossing Stat5b-CA with Rag2−/− or μMT−/− mice." (PMID 34736527, 2021).
leukemia (continued). "A phosphonate prodrug based on Stafia‐1 inhibited STAT5a with selectivity over STAT5b in human leukemia cells, providing the first demonstration of selective in vitro and intracellular inhibition of STAT5a by a small‐molecule inhibitor." (PMID 31503360, 2020). "Constitutive phosphorylation of S193 on STAT5B has been detected in various lymphoid tumor cell lines as well as in primary cells from leukemia or lymphoma patients." (PMID 31963765, 2020). "More recently, gain-of-function (GOF) mutations in STAT5B and STAT3 have been found in patients with leukemias and lymphomas." (PMID 31963765, 2020). "The opposite gene regulation pattern of human STAT5B mutant and murine Stat5b−/− leukemias regarding IFN responses prompted us to compare the expression of a specific set of genes." (PMID 30679796, 2019). "Here, we investigated the role of STAT5 isoforms in BCR/ABL+ leukemia, a disease that ceases upon combined loss of STAT5A and STAT5B." (PMID 30679796, 2019). "We selected genes that were upregulated in the murine Stat5b−/− samples and explored their expression in human STAT5B mutant leukemia." (PMID 30679796, 2019). "Transgenic mouse models expressing either wt Stat5b, or ca Stat5a or ca Stat5b in hematopoietic lineages were used to study the role of STAT5A/B in leukemia." (PMID 31690038, 2019). "A better understanding of the complex role of STAT5B in leukemia will enable the development of precision medicine strategies to treat disease." (PMID 30679796, 2019). "Once established, Stat5b−/− cells maintain a reduced proliferative capacity and induce leukemia significantly later." (PMID 30679796, 2019). "In line, Stat5b−/− leukemic cells induced leukemia with a significantly prolonged disease onset, whereas Stat5a−/− cells rapidly caused a fatal disease superimposable to wild-type cells." (PMID 30679796, 2019). "Confirmation stems from experiments where we applied a leukemia model using retroviral infection in new-born mice: Stat5b−/− mice succumbed significantly later to leukemia." (PMID 30679796, 2019). "The prodrug Pomstafib-2 selectively inhibits tyrosine phosphorylation of STAT5b in human leukaemia cells and induces apoptosis in a STAT5-dependent manner." (PMID 28400581, 2017). "In CD8+ TCRαβ+ T-LGL leukemia altered signaling through STATs has been implicated in the leukemogenesis, based on the frequent occurrence in mutations in the STAT3 and/or STAT5b genes." (PMID 28407008, 2017). "The two transcription factors STAT5A and STAT5B are central signaling molecules in leukemias driven by Abelson fusion tyrosine kinases and they fulfill all criteria of drug targets." (PMID 25333255, 2014). "Furthermore, the impaired activation of STAT5b seems to be involved in the development of leukemia induced by BCR/ABL (breakpoint cluster region-Abelson oncogene)." (PMID 41463071, 2025). "Moreover, there is evidence suggesting that the activation of STAT5B plays a pivotal role in leukemia induced by the breakpoint cluster region–Abelson oncogene (BCR/ABL)." (PMID 38273387, 2024). "This is supported by the fact that activating STAT5B mutations and particularly STAT5BN642H also occur in T cell large granular lymphocytic leukemia, T cell prolymphocytic leukemia, and various γδ T cell–derived leukemias/lymphomas." (PMID 38618957, 2024). "This also suppressed STAT5b phosphorylation and induced apoptosis of leukemia cells." (PMID 37173951, 2023). "Given the high relapse rate, patients with STAT5B/RARA-positive leukemia might benefit from hematopoietic stem cell transplantation in the first remission." (PMID 35494081, 2022). "STAT5B is critical at two distinct steps of transformation; during the initial switch from a normal to a transformed cell as well as during the establishment and progression of leukemia in vivo." (PMID 30679796, 2019).
leukemia (continued). "At variance to STAT3 mutated patient, analyzing CD16, CD56, CD57 cell markers no specific immunophenotype distinguishing STAT5b mutated from wild type patients was evidenced among CD4+ T-LGL leukemia." (PMID 28977911, 2017). "Partial knockdown of the transcription factor STAT5 (STAT5A and STAT5B) in FLT3-ITD cells resulted in decreased ROS production, highlighting the oncogenic association between recurring somatic mutations and the necessity for leukaemia cells to maintain a state of oxidative dysfunction." (PMID 34679751, 2021). "Activation of signal transducers and activators of transcription (STAT) proteins may be critical to their oncogenic functions as demonstrated by the development of B-cell lymphoma/leukemia in transgenic (TG) mice overexpressing a constitutively activated form of Stat5b." (PMID 23457589, 2013). "Finally, the data provide molecular evidence that STAT5B may represent a specific therapeutic target in BCR-ABL-positive leukemia although the development of STAT5B-specific small molecule inhibitors may be difficult due to the high homology between STAT5A and STAT5B." (PMID 24836440, 2014). "In leukemia, STAT5A and STAT5B may have individual functions as the constitutive activation of either protein is capable to inflict a disease of a specific phenotype." (PMID 30679796, 2019). "To test whether the effect extends to human BCR/ABL+ leukemia, we ablated STAT5A or STAT5B via shRNA-mediated knockdowns in K562 cells." (PMID 30679796, 2019). "Ebf1 and Pax5 deletions, though not sufficient to induce leukemia of their own accord, can each induce leukemia in mice with constitutive STAT5b activation." (PMID 23487523, 2012). "More recently, dissection of the respective contributions of STAT5A and STAT5B in BCR-ABL-dependent transformation revealed that STAT5B, but not STAT5A, is a critical effector of BCR-ABL-driven leukemia development." (PMID 31963765, 2020).
breast cancer (36 papers, 2007 to 2025). A primary or metastatic malignant neoplasm involving the breast. "In comparison, STAT5A shows favorable prognostic associations in breast cancer but detrimental effects in hematologic malignancies, whereas STAT5B appears predominantly tumor-suppressive across epithelial cancers and protective in B-cell lymphomas." (PMID 41301421, 2025). "In conclusion, we suggested STAT5B a prognosis biomarker and associated with immune infiltration in breast cancer, providing more serviceable information on the role of STAT5B in tumorigenesis." (PMID 36862902, 2023). "In STAT5B, a deletion mutation (K583Nfs*16) in the DNA binding domain that resulted in a frameshift was found to correlate with colorectal cancer and breast cancer (Cosmic database COSV53180593)." (PMID 36232600, 2022). "Here we quantify for the first time levels of Stat5a and Stat5b over breast cancer progression, and explore their potential association with clinical outcome." (PMID 23036105, 2012). "STAT5B was a biomarker associated with prognosis and immune infiltration in breast cancer." (PMID 36862902, 2023). "In addition, STAT5b is significantly associated with a favorable PPS in breast cancer patients (HR =0.71 (0.55–0.9), P=0.0052)." (PMID 29326301, 2018). "PRL activates both Stat5a and Stat5b, which have 92% amino acid similarity, but are encoded by different genes and may mediate overlapping and distinct effects in breast cancer cells." (PMID 23758962, 2013). "β1- integrin-mediated migration of breast cancer cells to fibronectin was inhibited with STAT5b knockdown, and loss of STAT5b correlated with loss of directional migration and formation of multiple, highly contractile protrusions upon attachment to fibronectin." (PMID 19630967, 2009). "This suggests that both STAT5A and STAT5B promote cyclin D1 expression in breast cancer through interacting with different cofactors." (PMID 40507264, 2025). "Impaired intracellular STAT3, STAT5A and STAT5B signaling has been reported in various solid tumors such as prostate, colon, glioma, head and neck tumors, melanoma, hemoblastosis and breast cancer." (PMID 36765714, 2023). "In order to further verify the potential of STAT5B as therapy target of breast cancer, we then analyzed the correlation between STAT5B and drug sensitivity." (PMID 36862902, 2023). "The univariate and multivariate analysis revealed that STAT5B, age, pT stage, pN stage and pM stage were independent factors affecting the prognosis of breast cancer patients." (PMID 36862902, 2023). "STAT5b silencing significantly inhibited invasion of a metastatic breast cancer cell line (T47D), compared to controls." (PMID 30558204, 2018). "Both high STAT5a and STAT5b mRNA expression are associated with a favorable OS and PFS in breast cancer patients." (PMID 29326301, 2018). "An analysis of multiple breast cancer cell lines showed that STAT5b is often constitutively phosphorylated at Y699 and activated." (PMID 30558204, 2018). "Our results indicated that STAT3, STAT4, STAT5a, STAT5b, and STAT6 were significantly associated with favorable OS in breast cancer patients, especially for high pathological grade patients." (PMID 29326301, 2018). "During normal mammary gland development, STAT5A plays the more dominant role, whereas both STAT5A and STAT5B have been described as contributing to breast cancer pathophysiology." (PMID 27472371, 2016). "Of particular interest, it has been previously reported that STAT5B induces the transcription of Hsp90, a molecular chaperone protein widely expressed in breast cancer." (PMID 26416415, 2015). "Recently, it has been shown that methylsulfonylmethane (MSM), a natural compound without any known toxicities, effectively inhibits the STAT3/VEGF and STAT5B/insulin-like growth factor receptor (IGF-1R) pathways in human breast cancer cells." (PMID 24913037, 2014).